CXCL2 (C-X-C motif chemokine ligand 2)
Diseases named in the same sentence as CXCL2 in open-access papers (continued):
Sharing a sentence is not in itself a finding about the gene and the disease.
bacterial infection (32 papers, 2014 to 2025). "We also determined the levels of the chemokines C-X-C motif ligand 1 (CXCL1) and CXCL2, both of which are important for neutrophil attraction during bacterial infection." (PMID 40359428, 2025). "Analysis of proinflammatory cytokines and chemokines at different time points showed significant upregulation of Tnf, Mmp14, Il1b, Il1a, Il17ra, Cxcl1, Cxcl2, Ccrl2, Ccl3, Ccl4, and Ccl9 after bacterial infection." (PMID 41117166, 2025). "In bacterial infections, a CARD9 deficiency results in a decrease in inflammatory cytokines (IL-1β, IL-6, and TNF-α) and chemokines (CXCL1, CXCL2, and CXCL5)." (PMID 38473845, 2024). "Previous studies have shown that Cxcl1/Cxcl2/Il1b axis in neutrophils plays a major role in inflammatory response during bacterial infections." (PMID 38149246, 2023). "For example, the production of neutrophil chemoattractants such as KC (CXCL1) and MIP2 (CXCL2) is diminished after secondary bacterial infection." (PMID 38138118, 2023). "Nevertheless, in some situations type 1 IFNs can also increase the host susceptibility to subsequent bacterial infection through impaired macrophage recruitment with a reduced CXCL1 and CXCL2 transcription and a reduced IL17 production." (PMID 32546263, 2020). "The heat map showed that the gene expression levels of 62 DEGs were upregulated and that some of these genes, such as IL-6, IL-1β, CCL2, CXCL2, CXCL8, and CSF3, are closely associated with host defense responses to bacterial infection." (PMID 31737164, 2019). "High levels of proinflammatory cytokines are observed during bacterial infection in CF patients, including IL-8 (a human analog of CXCL2 in mouse) and TNF-α." (PMID 29755959, 2018). "In conclusion, the multifunctional chemokines CCL3 and CXCL2 are produced locally in response to bacterial infection of bones." (PMID 24795505, 2014). "The predominant cell types in the lung expressing the two CXCL-8 homologs CXCL-1 and CXCL-2 during bacterial infections are alveolar macrophages and pulmonary epithelial cells." (PMID 25033194, 2014). "Furthermore, we identify the p38-MAPK pathway as a central regulator of ARG2-enriched CXCR2Hi MDSCs, with its activation leading to increased ARG2 expression and CXCL2 production in response to bacterial infections." (PMID 40860137, 2025). "Moreover, the experimental results indicate that IL-1 signaling promotes the production of leukocyte attractant chemokines CXCL-1 and CXCL-2 and recruitment of neutrophils to bacterial infection sites." (PMID 33525468, 2021). "The data presented here indicate that L-1R signaling is essential for CXCL1 and CXCL2 production upon exposure to GAS and S. aures and for neutrophil recruitment in a major target organ during bacterial infection." (PMID 33525468, 2021). "Particularly, despite failure to control bacterial infection, the P-DIE mice were shown to produce high levels of CXCL1 and CXCL2 in the peritoneum and blood that promoted neutrophil infiltration." (PMID 34367170, 2021). "In a sublethal P. aeruginosa pulmonary infection, PvdQ treatment resulted in less lung inflammation as well as decrease of CXCL2 and TNF-α levels at 24 h post-bacterial-infection by 15 and 20%, respectively." (PMID 29755959, 2018).
inflammation (18 papers, 2013 to 2025). Aberrant reaction of the microcirculation characterized by movement of fluid and leukocytes from the blood into extravascular tissues. "Comparative single-cell RNA-Seq (scRNA-Seq) analysis of direct and remote lung inflammation revealed that alveolar macrophages produced CXCL2 only during direct lung inflammation." (PMID 40048367, 2025). "Pulmonary inflammation was also assessed by quantifying Il-6, Tnf, Cxcl2 and Cxcl5 mRNA expression levels in lung tissue." (PMID 34717665, 2021). "In line with results from the RV‐induced airway inflammation model, increased mRNA expression of Cxcl1, Cxcl2, and Ifitm1 in HDM‐stimulated Mir146a/b−/− splenocytes was detected." (PMID 34185416, 2021). "To assess whether neutrophils are, in principle, able to extravasate during AKI-induced remote lung inflammation, we instilled CXCL2 i.t. just after sham or AKI." (PMID 40048367, 2025). "To define possible mechanisms underlying lung damage in DSS-treated TCRδ-/- mice, we analyzed the expression of genes encoding cytokines and chemokines known to contribute to predominately neutrophilic lung inflammation including Csf3, Cxcl2, Il17a, and the monocyte chemoattractant Ccl2." (PMID 37063825, 2023). "Similarly, our previous study revealed that ambient PM strongly induces neutrophilic airway inflammation through macrophage inflammatory protein (MIP)-2 (MIP-2/CXCL2), which is a murine homologue of IL-8, and IL-6 in a mouse model of asthma." (PMID 29882826, 2018). "Several genes that are involved in mucosal protection and immunity, such as Cxcl2 and IL-12A, retain levels of expression that are comparable to those observed in WT C57BL/6 mice and Lcn2, a gene that has been associated with gut inflammation, was detected at higher levels in Casp1−/− mice." (PMID 23977202, 2013). "Systemic and pulmonary inflammation was measured by enzyme-linked immunosorbent assays of plasma and bronchoalveolar lavage (BAL), respectively, which included tumor necrosis factor alpha (TNF-α), interleukin 6 (IL-6), IL-10, C-X-C motif ligand 2 (CXCL2), and CXCL5." (PMID 38928327, 2024). "Thus, LPS on the particles may have an important role in inducing neutrophilic airway inflammation via MIP-2/CXCL2 and IL-6 elevation." (PMID 25386753, 2014). "LPS-induced acute lung inflammation was significantly exacerbated in Spred-2−/− mice compared with WT mice, as indicated by the numbers of infiltrating leukocytes, levels of alveolar TNF-α, CXCL2 and CCL2 in a later phase, and lung pathology." (PMID 25275324, 2014). "While expression of Cxcl2 was not increased in the livers of our mice at this time point, it may be that the expression neutrophil chemokines happens earlier post-ethanol exposure as seen in other liver inflammation models." (PMID 34556145, 2021).
cardiovascular diseases (10 papers, 2015 to 2024). "The CXC motif chemokine ligand 2 (CXCL2) has been shown to be implicated in the pathogenesis of cardiovascular disease." (PMID 39135337, 2024). "Upregulated CXCL2 expression and secretion may favor the development of cardiovascular diseases, while the fast increase of CXCL12 in peripheral blood platelets can be used as biomarker for cardiac injury." (PMID 34084749, 2021). "However, the exact mechanism by which CXCL2, as an important inflammatory chemokine, acts in cardiovascular disease remains unclear." (PMID 39135337, 2024).
adenocarcinoma (5 papers, 2011 to 2025). A common cancer characterized by the presence of malignant glandular cells. "Of these, CXCL2 has previously been shown to be regulated by NFAT in microglia, and Cxcl8 expression was reported to depend on NFAT in adenocarcinoma cells." (PMID 25550437, 2015).
colorectal (5 papers, 2012 to 2025). "The LMP7-dependent up-regulation of CXCL1, CXCL2, CXCL3 and VCAM-1 expression leads to alternations in the microenvironment of tumors and progression of colorectal carcinogenesis." (PMID 28881574, 2017).
infectious disease (3 papers, 2017 to 2021). A disorder directly resulting from the presence and activity of a microbial, viral, or parasitic agent in humans. "We checked the expression of CXCR2, which is the main chemokine receptor on neutrophils for CXCL1 and CXCL2, because expression of CXCR2 is critically important for neutrophil associated protection against various infectious diseases." (PMID 28817707, 2017).
immune disorders (2 papers, 2021 to 2022). "Based on the immune regulation function of chemokines (including CXCL2) and its feedback loop mechanism, chemokines may be used as targets for the treatment of diseases related to immune disorders." (PMID 34721432, 2021).
nephropathy (2 papers, 2020 to 2022). A nonspecific term referring to disease or damage of the kidneys. "Of note, in our kidney mRNA assessment, we did not see a significant change in Ccl3 or Cxcl2 mRNA changes; this likely reflects that kidneys lack cells similar to stellate cells and that renal disease in SCD is not characterized by inflammatory cell infiltrates." (PMID 33542720, 2020).
neurological diseases (2 papers, 2015 to 2024). "However, among them, the literatures revealing the association of CXCL2 with various neurological diseases remain tiny." (PMID 40115159, 2024).
proliferative retinopathy (1 paper, 2023). "ELR+ CXC chemokines, including CXCL8 and CXCL2, are elevated in the vitreous body of diabetic patients with proliferative retinopathy." (PMID 36511116, 2023).
psychiatric disorder (1 paper, 2017). A disorder characterized by behavioral and/or psychological abnormalities, often accompanied by physical symptoms. "Ten genes were enrichedwith several KEGG pathways, and ROBO2, CXCL2, EPHA5,EPHA6, ANGPT2, FGF10, GHF genes was found to be enrichedwith pathways influencing psychiatric disorders like Axonguidance, RAP1 Signaling pathways, RAS Signaling pathwaysetc." (PMID 28539732, 2017).
vasculopathy (1 paper, 2019). "Thus, it also significantly alleviated inflammation presented by Chemokine (C-X-C motif) ligand 2 (Cxcl2), vasculopathy characterized by α-smooth muscle actin (α-SMA), and fibrotic changes elaborated by not only pathological images, but also the hydroxyproline (HYP) content." (PMID 31354856, 2019).
CXCL2 also shares sentences with these, for which no sentence is quoted: Insulin resistance (4 papers); chronic lymphocytic leukemia (3); Granuloma (3); lung diseases (3); multiple sclerosis (3); ZIKV infection (3); abdominal aortic aneurysm (2); acute myocardial infarction (2); Airway obstruction (2); allergic dermatitis (2); bacterial pneumonia (2); Cerebral ischemia (2); chorioamnionitis (2); colorectal adenocarcinoma (2); complication (2); cutaneous melanoma (2); dementia (2); dysplasia (2); emphysema (2); endometritis (2); endothelial dysfunction (2); glaucoma (2); head and neck cancer (2); heart failure (2); liver cirrhosis (2); pancreatic ductal adenocarcinoma (2); respiratory diseases (2); staphylococcus aureus infection (2); steatosis (2); stomach adenocarcinoma (2).
A further 97 diseases each share a sentence with CXCL2 in 2 papers or fewer.